SLC8A1 (solute carrier family 8 member A1)
Description:
Mediates the exchange of one Ca(2+) ion against three to four Na(+) ions across the cell membrane, and thereby contributes to the regulation of cytoplasmic Ca(2+) levels and Ca(2+)-dependent cellular processes. Contributes to Ca(2+) transport during excitation-contraction coupling in muscle. In a first phase, voltage-gated channels mediate the rapid increase of cytoplasmic Ca(2+) levels due to release of Ca(2+) stores from the endoplasmic reticulum. SLC8A1 mediates the export of Ca(2+) from the cell during the next phase, so that cytoplasmic Ca(2+) levels rapidly return to baseline. Required for normal embryonic heart development and the onset of heart contractions (By similarity).
Synonyms: NCX1
Tractability: Small molecule: a structure with a bound ligand is known. Antibody: UniProt places it where antibodies can reach, with high confidence; its Gene Ontology location is reachable by antibodies, with high confidence; UniProt predicts a signal peptide or a membrane-spanning region; the Human Protein Atlas places it where antibodies can reach. PROTAC: its protein half-life has been measured; a small molecule that binds it is known.
Target class: SLC08 family of sodium/calcium exchangers; SLC superfamily of solute carriers; Transporter; Electrochemical transporter
Gene: Protein-coding gene on chromosome 2 (40,097,270 to 40,611,053, reverse strand). Ensembl gene ENSG00000183023.
Subcellular location: Cell membrane
Subcellular location (Human Protein Atlas): Nucleoplasm; Plasma membrane
Pathways (Reactome):
Hemostasis: Reduction of cytosolic Ca++ levels
Muscle contraction: Ion homeostasis
Transport of small molecules: Sodium/Calcium exchangers
Gene Ontology:
Molecular function: ankyrin binding; calcium:sodium antiporter activity; calmodulin binding; cytoskeletal protein binding; protein binding; calcium ion binding; transmembrane transporter binding
Biological process: calcium ion import; calcium ion transmembrane transport; intracellular sodium ion homeostasis; positive regulation of bone mineralization; positive regulation of the force of heart contraction; response to muscle stretch; sodium ion import across plasma membrane; sodium ion transmembrane transport; calcium ion export across plasma membrane; calcium ion homeostasis; calcium ion transmembrane import into cytosol; calcium ion transport into cytosol; cardiac muscle cell development; cardiac muscle contraction; cell communication by electrical coupling involved in cardiac conduction; cellular response to caffeine; intracellular calcium ion homeostasis; membrane depolarization during cardiac muscle cell action potential; muscle contraction; negative regulation of cytosolic calcium ion concentration; negative regulation of intracellular signal transduction; regulation of cardiac conduction; regulation of cardiac muscle contraction by calcium ion signaling; regulation of cardiac muscle contraction by regulation of the release of sequestered calcium ion; regulation of cell communication by electrical coupling; and 9 more
Cellular component: cell periphery; plasma membrane; synapse; axon; axon terminus; dendrite; intercalated disc; neuronal cell body; postsynapse; postsynaptic density; sarcolemma; T-tubule; Z disc; membrane
Genetic constraint (gnomAD): Loss-of-function variants: 16 observed, 66.95 expected, observed/expected ratio (o/e) 0.24, 90% interval 0.16 to 0.36. The upper end of that interval is the gene's LOEUF score, 0.36, which puts it in group 1 of 6, group 1 being the genes least tolerant of losing a copy. Missense variants: 970 observed, 1,198.4 expected, observed/expected ratio (o/e) 0.81, 90% interval 0.77 to 0.85. Synonymous variants: 470 observed, 433.53 expected, observed/expected ratio (o/e) 1.08, 90% interval 1 to 1.17.
Homologues: Orthologues: chimpanzee SLC8A1 (99% identical), macaque SLC8A1 (99% identical), pig SLC8A1 (98% identical), dog SLC8A1 (98% identical), guinea pig SLC8A1 (97% identical), rabbit SLC8A1 (97% identical), rat Slc8a1 (95% identical), mouse Slc8a1 (95% identical), tropical clawed frog slc8a1 (88% identical), zebrafish slc8a1b (77% identical), zebrafish slc8a1a (76% identical). Paralogues in human: SLC8A3 (67% identical), SLC8A2 (63% identical), ADGRV1 (33% identical), FREM2 (22% identical), FREM1 (18% identical), FREM3 (17% identical), FRAS1 (17% identical).
Diseases named in the same sentence as SLC8A1 in open-access papers:
SLC8A1 is named in the same sentence as 131 diseases in open-access papers, as found by Europe PMC text mining. Sharing a sentence is not in itself a finding about the gene and the disease. The quoted sentences say what the papers report.
heart failure (44 papers, 2007 to 2025). Inability of the heart to pump blood at an adequate rate to meet tissue metabolic requirements. "The host gene Slc8a1, which encodes Na+/Ca2+ exchangers 1(NCX1), regulates cellular Ca2+ homeostasis and affects heart failure." (PMID 37371137, 2023). "The influence of SLC8a1-604 on heart function regulation highlights the clinical perspective of understanding circRNA-mediated translation events, offering new avenues for therapeutic interventions in heart failure." (PMID 40273295, 2025). "These SLC8a1-604 transgenic mice exhibited a heart failure phenotype." (PMID 40273295, 2025). "In the datasets for mouse, rat dataset 1 and human reference genes, we originally included a test set of 4 commonly queried transcripts in the heart failure literature (Apt2a2, Pln, Slc8a1, Nppa) to test the impact of choice of reference genes on gene expression ratios (MI/Sham or Failing/Donor)." (PMID 20331858, 2010). "Exemplifying its therapeutic potential, this study deployed a short-hairpin RNA to target and inhibit endogenous circRNA Slc8a1, which in turn resulted in the disinhibition of miR-133a and reduction of pathological hypertrophy and fibrosis in the model of pressure-overload-induced heart failure." (PMID 38485860, 2024). "Like circRNA Slc8a1, circRNA HIPK3 has been shown to sponge miR-133a in a model of MI, enhancing Notch1 and connective tissue growth factor (CTGF) expression thereby driving proliferation, migration, and fibrosis in a manner protective against heart failure." (PMID 38485860, 2024). "Second, a number of mouse models that exhibit mid-embryonic demise from heart failure exhibit abnormal cardiac mitochondria and mitochondrial dysfunction, including mice lacking Dbh, Nfactc3/Nfatc4, Rxra, and Slc8a1." (PMID 25427064, 2014).
Arrhythmia (17 papers, 2015 to 2024). Any cardiac rhythm other than the normal sinus rhythm. "In addition, SLC8A1/NCX1 can induce a variety of heart defects, such as VSD and arrhythmia." (PMID 36035156, 2022).
Hypertension (15 papers, 2009 to 2022). The presence of chronic increased pressure in the systemic arterial system. "Accordingly, a significant association with SBP and hypertension regarded SLC8A1 locus in a recent study of candidate genes for BP regulation in KoraS3 cohort." (PMID 21573014, 2011). "SLC8A1, that codes for Na+/Ca2+ exchanger type 1 NCX1 is one of the best candidate molecule in the biochemical control of peripheral vascular resistance and its role in the pathogenesis of hypertension and salt-sensitivity has been previously demonstrated." (PMID 21573014, 2011). "In total, 12 markers in 7 genes (ADRA2A, LEP, LEPR, PTGER3, SLC2A1, SLC4A2, SLC8A1) revealed considerable association (P<10−3) either with SBP, DBP, and/or hypertension (HYP)." (PMID 19562039, 2009).
cardiac hypertrophy (13 papers, 2013 to 2024). "Previous studies showed that overexpression of SLC8A1/NCX1 was associated with myocardial hypertrophy." (PMID 36035156, 2022).
cardiomyopathies (8 papers, 2013 to 2024). "Several calcium ion channels involved in cardiomyopathies are associated with TOP2B peaks including the voltage-dependent calcium channel CACNA1C, the sarcoplasmic reticulum calcium release channel RYR1, and the Na+/Ca+ exchanger and calcium anti-porter SLC8A1." (PMID 26459242, 2015). "We selected the sodium/calcium exchanger Slc8a1 (solute carrier family 8 member A1), involved in several KEGG-constructed signaling pathways (ASC, calcium, cGMP-PKG), as well as in CMC and the cardiomyopathies DIL and HCM, to illustrate the expression correlation." (PMID 38534766, 2024).
colon cancer (6 papers, 2017 to 2024). "The SLC8A1 gene is involved in calcium reabsorption and homeostasis, which regulates proliferation and apoptosis in many cells, including colon cancer cells." (PMID 39385172, 2024).
myocardial infarction (6 papers, 2022 to 2024). Gross necrosis of the myocardium, as a result of interruption of the blood supply to the area, as in coronary thrombosis. "Regarding myocardial infarction, a study of high-throughput RNA sequencing found that 3,862 circRNAs are dysregulated in peripheral blood, and the differentially expressed circ-TMEM165, circ-UBAC2, circ-ZNF609, circ-ANKRD12, and circ-SLC8A1 are confirmed in the AC16 cell model." (PMID 37840751, 2023).
Obesity (6 papers, 2016 to 2025). Accumulation of substantial excess body fat. "Until now, the specific roles of ANO2, CAMK2D, SLC8A1, PDE2A, CALML3, GNG7, and CALML6 genes in olfactory-related dietary patterns and obesity in humans have not been apparently explored; therefore, further investigation in these research areas is warranted." (PMID 31057674, 2019).
lung adenocarcinoma (4 papers, 2022 to 2023). A carcinoma that arises from the lung and is characterized by the presence of malignant glandular epithelial cells. "We present the first case of a rare SLC8A1 downstream intergenic region of ALK fusion in an advanced lung adenocarcinoma patient treated effectively with ceritinib using powerful NGS." (PMID 36042596, 2022). "Here, we reported a patient with advanced lung adenocarcinoma harboring a SLC8A1-ALK fusion who benefited from first-line treatment with alectinib." (PMID 36045716, 2022).
myeloma (4 papers, 2017 to 2024). "In contrast, SLC8A1 was only identified as significantly up-regulated in multiple myeloma." (PMID 34197603, 2021).
penile carcinoma (4 papers, 2016 to 2020). "Muñoz reported that lower levels of SLC8A1, which was at least partly mediated by miR-223, was associated with reduced calcium and apoptosis levels in penile carcinoma." (PMID 31827401, 2019).
ovarian carcinoma (3 papers, 2015 to 2024). A malignant neoplasm originating from the surface ovarian epithelium. "In this context, the authors documented a strong SLC8A1 downregulation in several drug-resistant ovarian cancer cell lines, claiming that it could represent an interesting therapeutic target for this malignancy." (PMID 26652480, 2015).
autism (2 papers, 2020 to 2025). Persistent deficits in social interaction and communication and interaction as well as a markedly restricted repertoire of activity and interest as well as repetitive patterns of behavior. "Other important genes suggested as being related to autism, such as CACNA1A and SLC8A1, also appeared, although targeted by a smaller number of miRNAs." (PMID 40282383, 2025).
bladder cancer (2 papers, 2022 to 2025). "ZNF503-AS1 acts as a tumor suppressor in bladder cancer by recruiting transcription factor GATA6 to up-regulate SLC8A1, which increases intracellular Ca2+ concentration." (PMID 40909272, 2025). "A cytoplasmic circRNA, circ-solute carrier family 8 member A1, sponges miR-130b/miR-494 and suppresses the progression of bladder cancer." (PMID 35288538, 2022).
endometrial cancer (2 papers, 2022 to 2024). Primary or metastatic malignant neoplasm involving the endometrium (mucous membrane that lines the endometrial cavity). "Solute carrier family 8, member 1 (SLC8A1), encoding the Na+/Ca2+ exchanger, has been found to regulate the traction force and promote the migration of endometrial cancer cells." (PMID 36231119, 2022). "The results indicated a significant decrease in the traction force of endometrial cancer cells after SLC8A1 overexpression and an increase in the knockdown group." (PMID 38882004, 2024).
glioma (2 papers, 2019 to 2025). A benign or malignant brain and spinal cord tumor that arises from glial cells (astrocytes, oligodendrocytes, ependymal cells). "Additionally, we identified five genes that not been implicated in glioma previously: CEP192 (18p11.21), D2HGDH (2q37.3) FAIM (3q22.3), HBEGF (5q13.3) and SLC8A1 (2p22.1)." (PMID 39565278, 2025).
neuroblastoma (2 papers, 2008 to 2020). Neuroblastoma (NB) is the most common solid, extracranial childhood tumor. "In comparison, SLC8A1 is involved in NO‐induced cellular toxicity in neuroblastoma cells, astrocytes, and microglia through a cGMP/protein kinase G (PKG)‐dependent mechanism." (PMID 32715657, 2020).
osteoporosis (2 papers, 2021). A condition of reduced bone mass, with decreased cortical thickness and a decrease in the number and size of the trabeculae of cancellous bone (but normal chemical composition), resulting in increased fracture incidence. "For instance, circ-SLC8A1 modulates osteoporosis via occluding the inhibited impacts of miR-516b-5p on the expression of AKAP2." (PMID 33869627, 2021). "Circ‐SLC8A1 acted as a promotive role in the development of osteoporosis through regulating miR‐516b‐5p/AKAP2." (PMID 34490735, 2021). "Ectopic expression of circ‐SLC8A1 promoted ALP, BGLAP, SPP1 and BMP4 expression and silenced circ‐SLC8A1 inhibited ALP, BGLAP, SPP1 and BMP4 expression, and it suggested that circ‐SLC8A1 acted as promotive role in the development of osteoporosis." (PMID 34490735, 2021).
Sepsis (2 papers, 2022 to 2024). Sepsis is defined as life-threatening organ dysfunction caused by a dysregulated host response to infection. "Low expression of ARHGEF10L in CD14 + monocytes is associated with increased death from sepsis, and the list included genes related to anti-bacterial activity (LCN2), regulation of TLR4 responses (SLC15A3), LPS sensitivity and autophagy (RUBCNL and SLC8A1) and apoptosis (FAS, TNFRSF21, TNFRSF8)." (PMID 39730996, 2024).
aromatase deficiency (1 paper, 2021). Aromatase deficiency disrupts the synthesis of estradiol, resulting in hirsutism of mothers during gestation of an affected child; pseudohermaphroditism and virilization in women; and tall stature, osteoporosis and obesity in men. "SLC8A1 (solute carrier family 8 member A1) is a protein-coding gene linked to multiple diseases, such as long Qt syndrome 9, cardiac diseases and aromatase deficiency." (PMID 33838653, 2021).
chronic bronchitis (1 paper, 2026). A type of chronic obstructive pulmonary disease characterized by chronic inflammation in the bronchial tree that results in edema, mucus production, obstruction, and reduced airflow to and from the lung alveoli. "Neutrophil-specific genetic deletion of Slc8a1 or pharmacological inhibition of NCX1 reverse transport effectively suppresses Ca2+ influx, NETs release, and neutrophil accumulation and retention, thereby ameliorating chronic bronchitis and emphysematous changes." (PMID 41813659, 2026).
colorectal adenoma (1 paper, 2023). An adenoma that arises from the colon or rectum. "We studied the relationship between calcium reabsorption genes SLC12A1, KCNJ1 and SLC8A1 and colorectal adenomas." (PMID 37074453, 2023).
coronary artery aneurysms (1 paper, 2020). "A recent study has confirmed that homozygous KD patients for the SLC8A1 A (risk) allele of rs13017968 were more likely to develop coronary artery aneurysms, which suggested the activation and importance of calcium signaling pathway in KD patients with CALs." (PMID 32183825, 2020).
Dravet syndrome (1 paper, 2022). "An ATP6V0C de novo variant had been reported in a SCN1A-negative patient with Dravet syndrome while the patient simultaneously harbored de novo missense variants in the genes of NKAIN3 and SLC8A1." (PMID 35600075, 2022).
ischemic cardiomyopathy (1 paper, 2024). Ischemic cardiomyopathy is a cardiomyopathy in which a weakness in the muscle of the heart due to inadequate oxygen delivery to the myocardium with coronary artery disease being the most common cause. "The Slc8a1 gene encodes the circRNA Slc8a1 (circSlc8a1), highly expressed in cardiomyocytes and implicated in a variety of cardiac disease states including ischemic cardiomyopathy and pressure-overload-induced heart failure." (PMID 38485860, 2024).
mycoplasma infection (1 paper, 2019). "Besides, a growing body of evidence have shown that SLC8A1, male, infants < 6 months old, low serum albumin, high ESR, CRP, mycoplasma infection, IVIG started after the 10th day of illness and IVIG non-responders may increase the risk of CAA." (PMID 31366406, 2019).
Sciatica (1 paper, 2021). Pain in the lower back and hip radiating in the distribution of the sciatic nerve. "We also found that TLR5, IL1RN, and SLC8A1 were upregulated in sciatica patients at baseline compared with healthy controls and downregulated after integrated TCM treatment compared with baseline, indicating that these genes played an important role in the pathogenesis and remission of sciatica." (PMID 33573686, 2021). "The roles of SLC8A1, RBM20, GPER1, IL27, SOCS1, and GRTP1-AS1 in sciatica or in relieving sciatica are currently unknown." (PMID 33573686, 2021).
tuberculosis (1 paper, 2024). A chronic, recurrent infection caused by the bacterium Mycobacterium tuberculosis. "The results showed that circRNA_SLC8A1 as a sponge of miR-20b-5p was upregulated in tuberculosis patients and inhibited miR-20b-5p expression." (PMID 38433218, 2024). "We showed that circRNA_SLC8A1 was upregulated in tuberculosis patients." (PMID 38433218, 2024). "In summary, we demonstrated that circRNA_SLC8A1 was upregulated in tuberculosis patients, and overexpression of circRNA_SLC8A1 sponged miR‐20b‐5p to upregulate SQSTM1/p62 expression, further activating the NF-κB signaling pathway to promote Mtb survival in macrophages." (PMID 38433218, 2024). "This study implies circRNA_SLC8A1 as a potential therapeutic target for tuberculosis control." (PMID 38433218, 2024).
uveal melanoma (1 paper, 2023). A melanoma derived from melanocytes of the uveal tract. "In striking contrast, expression of SLC8A1 is significantly associated with worse survival in uveal melanoma patients." (PMID 37966164, 2023). "Our data extend these previous findings by showing that LKB1 loss increases SLC8A1 expression and intracellular Ca2+ concentration in uveal melanoma." (PMID 37966164, 2023). "In fact, here we demonstrated in vitro and in a xenograft model that LKB1 loss increases uveal melanoma cells' sensitivity to the combination of the SLC8A1 inhibitor, KB‐R7943 with MitoQ, the only mitochondrial antioxidant that has safely been used in clinical trials." (PMID 37966164, 2023). "The effect of SLC8A1 knockdown by siRNA on reducing metastatic uveal melanoma cell formation capacity was confirmed in a second LKB1‐KO clone (Fig EV2D and E)." (PMID 37966164, 2023). "To investigate the role of SLC8A1 in uveal melanoma biology, we first analyzed its expression in human metastatic uveal melanoma samples." (PMID 37966164, 2023). "In agreement with the expression pattern in primary uveal melanomas, data showed that SLC8A1 expression is heterogeneous in metastatic uveal melanomas." (PMID 37966164, 2023). "Based on the complementary role of SLC8A1 and mtROS in promoting LKB1‐deficient uveal melanoma cell proliferation, we next investigated the therapeutic relevance of these pathways on tumor growth in vivo." (PMID 37966164, 2023). "Together, SLC8A1 and mitochondrial ROS mediate uveal melanoma cell survival and their co‐targeting may represent a new therapeutic option." (PMID 37966164, 2023). "We further demonstrate that combination of an SLC8A1 inhibitor and a mitochondria‐targeted antioxidant promotes enhanced cell death efficacy in LKB1‐ and SIK2‐negative uveal melanoma cells compared to control cells." (PMID 37966164, 2023).